ENSG00000267168 (novel protein)
Gene: Protein-coding gene on chromosome 17 (76,732,978 to 76,738,522, forward strand). Ensembl gene ENSG00000267168.
Genetic constraint (gnomAD): Loss-of-function variants: 9 observed, 7.15 expected, observed/expected ratio (o/e) 1.26, 90% interval 0.74 to 1.87. That is too few expected variants to judge how well the gene tolerates losing a copy. Missense variants: 132 observed, 95.59 expected, observed/expected ratio (o/e) 1.38, 90% interval 1.2 to 1.6. Synonymous variants: 43 observed, 35.11 expected, observed/expected ratio (o/e) 1.22, 90% interval 0.96 to 1.58.